ZNF286A-TBC1D26 (ZNF286A-TBC1D26 readthrough (NMD candidate))
Gene: Protein-coding gene on chromosome 17 (15,699,552 to 15,745,940, forward strand). Ensembl gene ENSG00000255104.
Genetic constraint (gnomAD): Missense variants: 440 observed, 574.89 expected, observed/expected ratio (o/e) 0.77, 90% interval 0.71 to 0.83. Synonymous variants: 149 observed, 189.18 expected, observed/expected ratio (o/e) 0.79, 90% interval 0.69 to 0.9.